APOE (apolipoprotein E)
Diseases named in the same sentence as APOE in open-access papers (continued):
Sharing a sentence is not in itself a finding about the gene and the disease.
diabetes (continued). "Sharma and colleagues conducted an interesting experiment in ApoE-/- mice with streptozocin-induced diabetes." (PMID 37765019, 2023). "Our data showed that macular VD did not significantly differ among Normal, Alzheimer and SNAP AT(N) groups in individuals with MCI after adjustment for age, APOE ε4 status, hypertension, diabetes mellitus, dyslipidemia, heart disease, COPD and smoking habit." (PMID 36908784, 2023). "This study found that age, gender, education, BMI, stroke, diabetes, neighborhood socioeconomic status, and APOE carrier status were among the top predictors of cognitive trajectories." (PMID 35927250, 2022). "NOX1 expression is increased in the plaques of patients with cardiovascular events or diabetes, and deleting NOX1 reduces lesion area in both apolipoprotein E deficient (ApoE−/−) mice and in ApoE−/− mice after induction of diabetes." (PMID 36497101, 2022). "In conclusion, we demonstrated that diabetes worsened ARHL in ApoE KO male mice fed with a WD through apoptosis of the SGNs and cells in the SV." (PMID 36408520, 2022). "Participants who were Aβ+ had a higher frequency of APOE e4 genotype (62.7% vs. 48.5%, p < 0.001) but a lower frequency of hypertension (39.0% vs. 48.5%, p = 0.003) and diabetes (13.2% vs. 24.4%, p < 0.001) than those who were Aβ−." (PMID 35936766, 2022). "Age and BMI explained up to 12% and 9% of the variance of R2* iron, while APOE ε4 carrier status, hypertension, diabetes, hypercholesterolemia, sex and smoking explained 5% or less." (PMID 35951362, 2022). "This was reported in diseases such as Alzheimer’s, where an association between the cluster HV and the risk of this disease following adjustment for the apolipoprotein E gene (APOE4) status was detected, and in obese patients with type 1 diabetes mellitus." (PMID 36089590, 2022). "Fully Adjusted Model: MedDiet Score, sex, age, education, family history, APOE, physical activity, smoking, sleep, body mass index, hypertension, hypercholesterolemia, hyperglycaemia, diabetes, stroke, antihypertensive medication use, diabetic medication use." (PMID 36568511, 2022). "The effects of depletion of IL-10 in diabetic microglia were then assessed in a mouse model for cerebral atherosclerosis, ApoE (−/−) mice that receive STZ to develop diabetes." (PMID 35935990, 2022). "It was shown that ALK7 expression was obviously elevated in the aorta of ApoE−/− mice with type 2 diabetes mellitus." (PMID 36059980, 2022). "Considered together, these findings indicate that the ApoE KO male mice model shows the progression of diabetes by STZ injection." (PMID 36408520, 2022). "Taking into account the classification of FH and ApoE genotype, the following vascular risk factors were analyzed: (i) HCL; (ii) HPB; (iii) diabetes mellitus." (PMID 35629270, 2022). "The χ2 test revealed significant differences between cases and controls in terms of age, physical activity, CVD, diabetes, life-time history of depression, and APOE genotype." (PMID 36085081, 2022). "While age and BMI explained up to 12% and 9% of the variance in brain iron respectively, APOE ε4 carrier status, hypertension, diabetes, hypercholesterolemia and sex explained 5% or less, and smoking status did not explain any variance." (PMID 35951362, 2022). "Age, sex, ethnicity, education, APOE E4 status, caloric intake, BMI, duration between diet evaluation and MRI, smoking, diabetes, hypertension, and heart disease." (PMID 35571887, 2022). "Smoking status and number of vascular comorbidities (considering hypertension, hypercholesterolaemia and diabetes) were significant predictors as well as the APOE ε4 genotype and socioeconomic status." (PMID 35241774, 2022). "As expected, body weight decreased, blood glucose increased, and dyslipidemia (increased TC, TG, and LDLc, with decreased HDLc and apoE) was observed in the STZ-induced diabetes model, consistent with previous studies." (PMID 35669071, 2022).
diabetes (continued). "Age, sex, education, BMI, APOE E4 status, diabetes, stroke, blood pressure, cardiovascular disease, cognitive ability and MMSE." (PMID 35571887, 2022). "APOE is involved in lipid metabolism and can modulate the relationshipbetween vascular factors, diabetes, and cognitive functions." (PMID 33907599, 2021). "The associations remained significant after adjusted for age, gender, education year, APOE-ε4, hypertension, diabetes, baseline MMSE, and proteinuria." (PMID 33430940, 2021). "Metformin can inhibit the NLRP3 inflammasome activation in apolipoprotein E (apoE) -/- mice and inhibit diabetes-accelerated AS, at least in part by activating AMPK and regulating thioredoxin-1/thioredoxin interacting protein." (PMID 34163481, 2021). "GCG, IRS1, VEGFA, STAT3, CCL2, CASP3, and APOE as diabetes mellitus-related proteins and SREBF1, LPL, PPARA, APOB, GPT, MAPK8, and FASN as NAFLD-specific proteins were identified as possible discriminating factors between the two studied diseases." (PMID 35154608, 2021). "We also calculated the risk of OCI in patients with anemia based on various adjustments such as diabetes, stroke, education, APOE e4, and depression." (PMID 34208355, 2021). "In-vivo experiments showed that the overexpression of CTRP9 inhibited vascular senescence and reduced atherosclerotic plaque formation in ApoE KO mice with diabetes." (PMID 34744738, 2021). "The risk factors contributing to microbleeds include age, blood pressure, diabetes mellitus, low serum cholesterol, smoking, and apolipoprotein E (APOE) genotype." (PMID 34881076, 2021). "Mixed-effects model analyses were performed to evaluate the effects of APOE ε4, low education, hypertension, diabetes, dyslipidemia, and obesity on cognitive trajectories." (PMID 34127075, 2021). "In-vivo experiments showed that CTRP9 inhibited hyperglycemia-induced vascular senescence and reduced atherosclerotic plaque formation in ApoE KO mice with STZ-induced diabetes." (PMID 34744738, 2021). "Metformin can inhibit the NLRP3 inflammasome activation in ApoE-/- mice and inhibit diabetes-accelerated AS, at least in part by activating AMPK and regulating thioredoxin-1/thioredoxin interacting protein." (PMID 34163481, 2021). "We injected lentiviral vectors overexpressing CTRP9 into ApoE KO mice with STZ-induced diabetes that were fed a high-fat diet and found that overexpression of CTRP9 significantly inhibited senescence in the aorta and decreased atherosclerotic lesions." (PMID 34744738, 2021). "Multiple risk factors have been identified, including female gender, age, low education level, the apolipoprotein E (APOE * E4 allele), smoking, obesity, and diabetes mellitus." (PMID 34064930, 2021). "The alterations in the expression of these molecules were reversed in STZ-diabetic ApoE−/− mice treated with acacetin (p = 0.0399–0.0031 vs. STZ-diabetes)." (PMID 33519472, 2020). "We adjusted for confounders including gender, age, education, history of hypertension, diabetes, stroke, heart disease, and APOE-e4 genotype status." (PMID 32167487, 2020). "Contrary to the assumption of hypertension as the dominant risk factor associated with WMH load, we show the associations of similar magnitude with APOE ε4/ε4 status, WHR, diabetes and heavy smoking." (PMID 32971464, 2020). "Age was the strongest predictor followed by antihypertensive medication use, having diabetes and APOE status." (PMID 32895386, 2020). "Antihypertensive medication, diabetes and APOE status were all significant predictors of executive function." (PMID 32895386, 2020). "This interaction disappeared after additional adjustment for diabetes mellitus, ApoA-I, ApoB, ApoE, and Lp(a)." (PMID 32546151, 2020).
diabetes (continued). "We performed the proportional hazard regression analysis ranking patients according to Per2 polymorphism, including as covariates age at onset, age at baseline, ApoE genotype, hypertension, diabetes, dyslipidemia, heart disease, and smoking." (PMID 32485802, 2020). "The major risk factors of this multifactorial disease include apolipoprotein E ɛ4 (APOE ɛ4) genotype, family history, age, traumatic brain injury, hypercholesterolemia, obesity, hypertension, diabetes, and low education level." (PMID 32380758, 2020). "APOE ɛ4 status, sex, age, smoking status, history of cardiovascular disease, cerebrovascular disease, hypertension, and diabetes were included as covariates." (PMID 32111184, 2020). "Diabetes was associated with a greater than 3-fold elevation in UAE in both C57BL/6 and apoE KO mice (p < 0.0001)." (PMID 32581831, 2020). "Risk of AD development is associated with factors such as apolipoprotein-E (APO-E), diabetes mellitus, aging, smoking habits, and lower socio-economic status." (PMID 31941117, 2020). "After additional adjustment for gender, years of education, APOE ε4, and BMI, fasting status, and medications (supplements, diabetes, lipid lowing), the RF scores remained significant (as an independent predictor) with a coefficient of 7.828 (P-value < 0.001)." (PMID 32820198, 2020). "In both strains, diabetes was associated with an accumulation of extracellular matrix proteins in the mesangium (p < 0.05, C57BL/6; p < 0.001 apoE KO) compared to chow fed mice of the same strain respectively." (PMID 32581831, 2020). "We considered as covariates age at onset, age at baseline, ApoE, Clock and Per2 genotype, hypertension, diabetes, dyslipidemia, heart disease, and smoking habit." (PMID 32485802, 2020). "In our murine model of diabetes and hypercholesterolaemia, only the aorta of Ins2+/Akita mice and Ins2+/Akita: ApoE−/− mice featured greater expressions of ASMA and F‐actin." (PMID 31970899, 2020). "After adjusting for gender, years of education, APOE ε4, BMI, fasting status, and medications (supplement, diabetes, lipid lowing), the RF scores remained statistically significant as an independent predictor with a coefficient of 5.629 (P-value < 0.001)." (PMID 32820198, 2020). "The combination of MASP, apolipoprotein E (apoE) and adiponectin improved diabetes prediction on top of both reference models, while prediabetes prediction was improved by MASP plus CRP on top of the HbA1c model." (PMID 30599058, 2019). "Second, the combination of the circulating biomarkers MASP, apoE, adiponectin, HbA1c, age and sex predicted diabetes equally well as the GDRSadapted-variables and HbA1c." (PMID 30599058, 2019). "Normal ApoE−/− and diabetic mice were allocated to four groups (n = 15): normal diet, normal diet plus rutin, diabetic, and diabetes plus rutin." (PMID 31437127, 2019). "Associations of the 22 metabolites to CD were generally unchanged (or slightly strengthened) when further adjusting for ApoE‐ε4, diabetes and physical activity." (PMID 31218777, 2019). "Fully adjusted models identified increased age, APOE*4 carriage, depression, diabetes, history of stroke, and current smoking as independently associated with lower scores for 1 or both of the MMSE and global cognition composite." (PMID 31335910, 2019). "Higher levels of HGF were significantly associated with both CIND and AD after correction for age, gender, APOE ε4 carrier, hypertension, diabetes, and cardiovascular diseases." (PMID 29410622, 2018). "In type 1 diabetes mellitus and diabetic apolipoprotein E knockout (apoE−/−) mice, the expression ABCA1 was downregulated in the kidney." (PMID 29681863, 2018). "APOE ε4 status, age, sex, height, childhood IQ, smoking, history of cardiovascular or cerebrovascular disease, hypertension and diabetes were included as additional variables." (PMID 30180830, 2018).
diabetes (continued). "Third, we adjusted for important covariates, including GDS-K score, education duration, history of diabetes, history of hypertension, and apolipoprotein E ε4 genotype status." (PMID 29330465, 2018). "For PD, then, are there specific molecules like ApoE or VEGF or others directly linked to common cardiovascular risks such as hypertension, atherosclerosis, and diabetes?" (PMID 29342116, 2018). "Eight-week-old ApoE KO mice were treated with NA/STZ to induce diabetes mellitus, and then divided into two groups, either untreated, or treated with luseogliflozin." (PMID 28777298, 2017). "These group differences in the HOMA indices became statistically significant after co-varying for BMI, sex, diabetes, use of diabetes medication, smoking, age and APOE genotype." (PMID 28852028, 2017). "NLRP3, caspase-1, IL-1β, and IL-18 were minimally expressed in normal glomerular tissues, but were significantly up-regulated in diabetic apoE (-/-) and apoE (-/-) mice, with more prominent changes in diabetes apoE (-/-) mice." (PMID 28708885, 2017). "APOE e4 carriers with either a self-reported diagnosis of diabetes (β = 0.160, p = 0.002) or higher glycated hemoglobin levels (β = 0.114, p = 0.014) exhibited greater WMH progression, and the former survived correction for multiple testing." (PMID 28324763, 2017). "These proteins we considered to be diabetes-typical, including two members of the complement system, C4 and C9, ApoE, fibrillin, fibronectin, TIMP-3 and Prolargin/PRELP, a proteoglycan." (PMID 29284024, 2017). "Variables included: age, sex, age 11 IQ, APOE ɛ4, education, diabetes, hypertension, statin use, physical activity at leisure and in occupation, symptoms of depression, height, number of teeth, body mass index, blood pressure, cholesterol and HbA1c." (PMID 28578665, 2017). "Age, sex, history of hypertension, diabetes mellitus, typerlipidemia, education, APOE ε4 carrier status, alcohol drinking, smoking, physical activities and/or hobbies, and coffee consumption." (PMID 28496007, 2017). "After 20 weeks of diabetes, the mesangial areas significantly increased in diabetic apoE (-/-) mice compared to apoE (-/-) mice, and the mesangial expansion was significantly attenuated by PIO treatment." (PMID 28708885, 2017). "After 10 weeks of diabetes induction, ≈40% plaques in Tnfsf12+/+ApoE−/− were advanced plaques (grade IV) while only ≈10% plaques were early lesions (grade I)." (PMID 28447667, 2017). "In Finnish population, apoE genotypes were found to modulate the risk of coronary heart disease (CHD) and atherosclerotic vascular disease in non-insulin dependent diabetes mellitus (NIDDM)." (PMID 26800892, 2016). "ApoE−/− mice had a significant increase in total plaque area, which increased further after the induction of diabetes." (PMID 28070143, 2016). "Since, different apoE isoforms associate with significant variation in lipid profiles, the coding apoE gene is a candidate for CVD and/or diabetes." (PMID 26800892, 2016). "Per additional copy of the ApoE isoform (coded as: ε2 carrier = 0, ε3/ε3 = 1, ε4 carrier = 2), HDL cholesterol serum level decreased (p-valuetrend = 0.02) as well as the risk of diabetes (p-valuetrend = 0.04)." (PMID 27540764, 2016). "Of the investigated metabolic phenotypes, we found significant association between ApoE isoform and serum HDL cholesterol and diabetes risk (also rs7412)." (PMID 27540764, 2016). "The difference between DNA methylation age and chronological age predicts mortality risk over and above a combination of smoking, education, childhood IQ, social class, APOE genotype, cardiovascular disease, high blood pressure, and diabetes." (PMID 25633388, 2015). "Pharmacogenetic effects of the APOE genotype have also been found in response to therapeutic approaches used in diabetes, hyperlipidemia, and neurodegenerative diseases." (PMID 26074879, 2015).
diabetes (continued). "The novelty of this study is that the same dose of this bioflavonoid was capable of reducing the classical signs of diabetes and attenuated the progression of nephropathy in diabetic-induced apoE−/− mice." (PMID 26388784, 2015). "The results from our study showed that only the plasma HSP 70 level was associated with a conversion from NCI to MCI after adjustments for age, gender, years of education, follow-up duration, APOE e4 status, hypertension, and diabetes." (PMID 25768018, 2015). "In a model adjusting for baseline age, sex, education, diabetes mellitus, hypertension, smoking, prior history of stroke, and apolipoprotein E genotype, high anti-A." (PMID 25522313, 2014). "The APOE genotype predicted cardiovascular endpoints in dialysis patients with type 2 diabetes mellitus." (PMID 24571688, 2014). "We have previously demonstrated that in response to a high-fat diet (HFD) for 12 w, TRAIL gene deletion in ApoE-/- mice resulted in increased systemic inflammation, diabetes and accelerated atherosclerosis." (PMID 24667560, 2014). "Treating with soluble RAGE (s-RAGE) that binds ligands and thereby decreases RAGE expression reversed the effect of diabetes to accelerate lesion growth in apolipoprotein E null (apoE−/−) diabetic mice." (PMID 24829796, 2014). "The mean serum glucose levels for the apoE−/− mice with 6 weeks of diabetes and prior to insulin treatment were 364 ± 66 mg/dL for the mice that received the insulin implants and 360 ± 57 mg/dL for the mice that were followed as hyperglycemic controls." (PMID 24829796, 2014). "HFD treatment caused significant increases in body weight and plasma glucose levels at 8 w in TRAIL-/-ApoE-/- mice, consistent with the development of diet-induced diabetes." (PMID 24667560, 2014). "In the present study, we induced diabetes in ApoE KO atherosclerotic mice by injecting them with STZ." (PMID 24107300, 2013). "Data were analyzed with regression adjusted for age, gender, years of education and additionally for diabetes mellitus, cardiovascular diseases, alcohol use, smoking, inflammatory markers and apolipoprotein E genotype." (PMID 23483953, 2013). "BMP4 expression was also much greater in the whole aortas of diabetic ApoE KO mice compared with control mice, suggesting that diabetes also induces aortic BMP4 expression in db/db mice." (PMID 24107300, 2013). "Apolipoprotein E (apo E) plays a major role in lipid metabolism, obesity and accordingly in development of diabetes and coronary heart disease (CHD)." (PMID 23497440, 2012). "Because ApoE e4 status and some vascular risk factors [e.g., hypertension, hyperlipidemia, and type 2 diabetes mellitus (DM)] may affect the pathogenesis of dementia, this study further explored the effect of modification by these factors." (PMID 22272811, 2012). "Our study is the first to report that topical eye drop treatment of apoE mimetic peptide (apoEdp) is an effective and non-invasive approach to treat diabetes-induced retinal EC injury." (PMID 23284911, 2012). "The prevalence of diabetes was lower in the demented group, whereas the prevalence of stroke and APOE ε4 was higher." (PMID 20576093, 2010). "We overexpressed A20 in aortic arches of diabetic ApoE-null mice six weeks after documentation of diabetes (early stages of atherosclerotic lesion development) by administering rAd.A20 (5×109 pfu) through the left ventricle." (PMID 21151899, 2010). "Using this model, we found that after 10 weeks of diabetes mRNA levels of the CDA1-encoding gene Tspyl2 and profibrotic growth factors Tgf-β and Ctgf increased 1.5 to 2-fold in aortas of ApoE−/− mice." (PMID 24710090, 2010). "In ApoE−/− mice also deficient for TNFα, cholesterol levels were also increased by diabetes and this effect was more pronounced than in ApoE−/− mice." (PMID 20856927, 2010). "There was little suggestion of an interaction between hypertension, diabetes, or heart disease and APOE ε4 in fully adjusted models (P > 0.1)." (PMID 20576093, 2010).